CARMIL1 (capping protein regulator and myosin 1 linker 1)
Description:
Cell membrane-cytoskeleton-associated protein that plays a role in the regulation of actin polymerization at the barbed end of actin filaments. Prevents F-actin heterodimeric capping protein (CP) activity at the leading edges of migrating cells, and hence generates uncapped barbed ends and enhances actin polymerization, however, seems unable to nucleate filaments. Plays a role in lamellipodial protrusion formations and cell migration.
Synonyms: CARMIL; LRRC16; LRRC16A; dJ501N12.1; FLJ20048; CARMIL1a; dJ501N12.5
Tractability: Antibody: UniProt places it where antibodies can reach, with high confidence; its Gene Ontology location is reachable by antibodies, with high confidence; the Human Protein Atlas places it where antibodies can reach. PROTAC: ubiquitination databases record sites on it.
Gene: Protein-coding gene on chromosome 6 (25,279,078 to 25,620,537, forward strand). Ensembl gene ENSG00000079691.
Subcellular location: Cytoplasm; Cytoplasm, cytoskeleton; Cell membrane; Cell projection, lamellipodium
Subcellular location (Human Protein Atlas): Cytosol; Plasma membrane; Nuclear speckles
Pathways (Reactome):
Hemostasis: Factors involved in megakaryocyte development and platelet production
Gene Ontology:
Molecular function: protein binding; protein-containing complex binding
Biological process: actin filament network formation; cell migration; lamellipodium assembly; macropinocytosis; positive regulation of cell migration; positive regulation of lamellipodium organization; positive regulation of stress fiber assembly; positive regulation of substrate adhesion-dependent cell spreading; ruffle organization; urate metabolic process; actin filament organization; barbed-end actin filament uncapping; negative regulation of barbed-end actin filament capping; positive regulation of actin filament polymerization; regulation of Arp2/3 complex-mediated actin nucleation
Cellular component: cell leading edge; cytoplasm; cytosol; extracellular exosome; lamellipodium; macropinosome; plasma membrane; filamentous actin; cytoskeleton
Genetic constraint (gnomAD): Loss-of-function variants: 53 observed, 110 expected, observed/expected ratio (o/e) 0.48, 90% interval 0.38 to 0.61. The upper end of that interval is the gene's LOEUF score, 0.61, which puts it in group 2 of 6, group 1 being the genes least tolerant of losing a copy. Missense variants: 1,069 observed, 1,268.2 expected, observed/expected ratio (o/e) 0.84, 90% interval 0.8 to 0.89. Synonymous variants: 458 observed, 474.22 expected, observed/expected ratio (o/e) 0.97, 90% interval 0.89 to 1.04.
Homologues: Orthologues: chimpanzee CARMIL1 (99% identical), macaque CARMIL1 (99% identical), guinea pig CARMIL1 (94% identical), dog CARMIL1 (93% identical), pig CARMIL1 (92% identical), rat Carmil1 (90% identical), mouse Carmil1 (89% identical), rabbit CARMIL1 (85% identical), tropical clawed frog carmil1 (79% identical), Drosophila melanogaster LRR (33% identical), Caenorhabditis elegans crml-1 (21% identical), zebrafish carmil1 (5% identical). Paralogues in human: CARMIL3 (37% identical), CARMIL2 (31% identical), PPP1R37 (11% identical), RNH1 (8% identical).
Diseases named in the same sentence as CARMIL1 in open-access papers:
CARMIL1 is named in the same sentence as 7 diseases in open-access papers, as found by Europe PMC text mining. Sharing a sentence is not in itself a finding about the gene and the disease. The quoted sentences say what the papers report.
COVID-19 (1 paper, 2022). A disease caused by infection with severe acute respiratory syndrome coronavirus 2. "The CARMIL1 gene was highly expressed in diverse lung cells from severe COVID-19 patients; however, it was not expressed in PBMCs from healthy adults." (PMID 35913450, 2022).
mammary tumor (1 paper, 2021). "It was recently reported using orthotopic injection of 4T1 mouse mammary tumor cells (generated from CARMIL1-WT or CARMIL1-AA cells) into BALB/c mice to study the role of macropinocytosis in mediating treatment resistance." (PMID 32929562, 2021).
tumor (2 papers, 2020 to 2025). "Our results with CARMIL1-AA 4T1 tumors provide compelling evidence that necrocytosis can make a significant contribution to tumor anabolism and help to explain paradoxical observations that tumor cell death drives tumor growth." (PMID 32111826, 2020). "Upon termination of 5-FU treatment, tumor growth resumed, although at a slower rate for 5-FU-treated CARMIL1-AA than CARMIL1-WT tumors." (PMID 32111826, 2020). "CARMIL1-WT and CARMIL1-AA 4T1 cells were employed to measure the contribution macropinocytosis makes to tumor growth in vivo." (PMID 32111826, 2020). "By offering a more selective means to disable macropinocytosis in tumor cells than EIPA, the CARMIL1-AA mutant will facilitate future studies evaluating the role of macropinocytosis in tumor growth and progression." (PMID 32111826, 2020). "Because CARMIL1-AA is more selective than EIPA, these tumor growth assays also provide more rigorous support for the model that macropinocytosis drives solid tumor growth than published studies using EIPA3,4,8." (PMID 32111826, 2020).
CARMIL1 also shares sentences with these, for which no sentence is quoted: gout (8 papers); cancer (2); nephrolithiasis (1); schizophrenia (1).